ITGA3 (integrin subunit alpha 3)
Diseases named in the same sentence as ITGA3 in open-access papers (continued):
Sharing a sentence is not in itself a finding about the gene and the disease.
breast carcinoma (continued). "The integrin subunit alpha 3 (ITGA3), a member of the integrin family, has been identified as an important prognostic biomarker in several types of human cancers, including PCa, breast cancer, non-small cell lung cancer, and bladder cancer." (PMID 36561844, 2022). "The reduced adhesion to collagen I that we have observed in MDA-MB-231, SKBR3, and AU565 ITGA3 KO mammary carcinoma cells is not due to the changes in the α2β1 expression, but likely due to the reduced clustering of α2β1." (PMID 31101121, 2019). "(c-d) Scatter plots of ITGA3 and ERBB2 expression of breast cancer cell lines, classified as luminal-, basal-, and post-EMT-like show clustering of luminal-like cell lines to low ITGA3 expression: (c) HER2+ and triple-negative-enriched breast cancer panel (n = 30)." (PMID 31101121, 2019). "To assess whether α3β1 influences the invasive potential of HER-driven human mammary carcinoma cells, we generated SKBR3, AU565, and BT474 ITGA3 KO cell lines by CRISPR/Cas9 technology." (PMID 31101121, 2019). "To confirm differential gene expression levels in the three breast cancer subtypes, Her2+, ER + and TNBC, we selected 6 genes (ITGA3, ITGA5, OXTR, WNT5B, BCAR1, FZD1) with significantly different levels of expression based on our microarray studies and validated their expression levels by qRT-PCR." (PMID 22954256, 2012). "However, the expression and prognosis of ITGA3 in breast cancer have not been reported." (PMID 34094951, 2021). "(b) Scatter plot showing a lack of correlation between ITGA3 and ERBB2 expression in CCLE breast cancer panel (Spearman’s rho − 0.17, P = 0.22, n = 51)." (PMID 31101121, 2019).
bladder cancer (18 papers, 2020 to 2025). "Recently, a non-invasive assay has been described to identify fucosylated-glycoisoform of ITGA3 from unprocessed urine from bladder cancer patients." (PMID 39598633, 2024). "It was later confirmed, using EVs from bladder cancer cells or cancer patient urine, that ITGA3-UEA biomarker combination can successfully discriminate bladder cancer patients from those with benign tumors and prostate cancer patients." (PMID 36430846, 2022). "ITGA3, integrin alpha-3, was known to influence the development of various cancers including bladder cancer." (PMID 33925460, 2021). "While higher expression of APOL1, ATG4B, ITGA3, WDR45, CASP3, and PRKCD is associated with favorable survival in human bladder cancer patients, increased ULK2 and P4HB mRNA levels are negatively correlated to overall survival of bladder cancer patients." (PMID 33925460, 2021). "In a previous study, we reported fucosylated glycoisoforms of ITGA3 directly from unprocessed urine to distinguish bladder cancer from age-matched benign controls in a simple sandwich assay." (PMID 34638669, 2021). "When tested as individual gene, 9 genes from the 11-ARG signature (APOL1, ATG4B, CASP3, ITGA3, P4HB, PRKCD, ULK2, and WDR45) exhibited a significant association between mRNA expression levels and overall survival of bladder cancer patients." (PMID 33925460, 2021). "As a biomarker for bladder cancer, fucosylated-glycoisoform of integrin alpha-3 (ITGA3) from the urine of bladder cancer patients was utilized for bladder cancer diagnosis." (PMID 34948129, 2021). "ITGA3 is also overexpressed in bladder cancer and correlated with poor prognosis." (PMID 39598633, 2024). "ITGA3 belongs to the integrin family of cell surface receptors and is related to autophagy in various cancers, such as head and neck squamous cell carcinoma, bladder cancer, osteosarcoma, and glioblastoma." (PMID 35573972, 2022). "Upregulation of ITGA3 was observed in clinical specimens and bladder cancer cell lines." (PMID 33925460, 2021). "Similarly, miR-124-3p blocks cell migration and invasion by affecting the combined integrin subunit alpha-3 signaling in bladder cancer." (PMID 34234863, 2021). "Similarly, we have developed ITGA3-UEA assay where fucose binding lectin UEA can detect the aberrant fucosylations of ITGA3 + EVs which could facilitate the detection of bladder cancer." (PMID 37773167, 2023). "Furthermore, based on the developed assay platform, we have identified a glycovariant of ITGA3 on urine of bladder cancer (BlCa) patients which could be used for BlCa detection." (PMID 37773167, 2023). "As previous studies have shown that ITGA3 activates FAK and Src signalling, which are involved in cell adhesion, migration, invasion, and proliferation in skin carcinoma, bladder cancer and cervical carcinoma, we investigated the potential regulation of FAK/Src signalling by ITGA3 in PTC cells." (PMID 40138447, 2025).
prostate carcinoma (15 papers, 2013 to 2023). A carcinoma that arises from epithelial cells of the prostate gland. "Only 4 types of cancers revealed the low expression of ITGA3 including breast, lung, colorectal, and prostate cancers, with 7 datasets involved in the group." (PMID 35174063, 2021). "Biotinylated anti-EpCAM, anti-ITGA3 or anti-CD63 antibodies were applied for capturing EVs from cell culture supernatants of the prostate cancer cell lines LNCaP, DU145 and PC3 and one of the control cell line HEK293." (PMID 31296879, 2019). "ITGA3 has been found to show aberrant expression in many malignant human tumors, including colorectal cancer, melanoma, and prostate cancer." (PMID 29511671, 2018). "Increased data have revealed that ITGA3 expression levels positively correlate with the prognosis of many malignant human tumors, including colorectal and prostate cancers." (PMID 29511671, 2018). "Our previous study showed that overexpression of ITGA3 enhanced cancer cell migration and invasion and directly regulated antitumor expression of miR-223 in prostate cancer." (PMID 28881803, 2017). "In prostate cancer, miR-223 suppressed tumor cell proliferation, migration, and invasion by targeting ITGA3/ITGB1 (integrin subunit alpha 3/ integrin subunit beta 1) signaling." (PMID 27618431, 2016). "Through our simple NPs-based assay, we reaffirmed their findings by showing higher expression of ITGA3 on the EVs obtained from more aggressive prostate cancer cell lines DU145 and PC3 compared to the less aggressive prostate cancer cell line LNCaP and HEK293 control." (PMID 31296879, 2019). "ITGA3 gene knockdown significantly decreases head and neck cancer cell migration and invasion, whereas suppression of miR-223 microRNA synthesis, which enhances intracellular signal transmission from ITGA3/ITGB1, stimulates cell motility in prostate cancer." (PMID 34503200, 2021). "In the present study, miR-233 was predicted to bind with circGNG4, and miR-223 has been determined to inhibit prostate cancer progression by targeting ETS transcription factor ERG (ERG) and integrin subunit α 3 (ITGA3)/integrin subunit β 1 (ITGB1) signaling." (PMID 34395419, 2021). "We also revealed that miR-223 acted as an antitumor miRNA through targeting ITGA3 and ITGB1 in prostate cancer." (PMID 29423074, 2018). "Our previous studies showed that overexpression of ITGA6/B4 and ITGA3/B1 was involved in cancer cell migration and invasion in HNSCC and prostate cancer." (PMID 28415821, 2017). "However, in addition to ERG and ITGA3/ITGB1 signaling, alternative target genes of miR-233 remain to be elucidated in prostate cancer." (PMID 34395419, 2021). "Also the downregulation of SNAI2, ITGA3, BCL2, PGR, IGFPB3 and HOXD10 was previously reported for prostate cancer." (PMID 28005952, 2016).
colorectal cancer (14 papers, 2014 to 2025). A primary or metastatic malignant neoplasm that affects the colon or rectum. "Similarly, miR-124-3p, which targets ITGA3, increases the anoikis susceptibility and inhibits the lung metastasis of colorectal cancer cells." (PMID 33435156, 2021). "Our chosen target inhibits proliferation, migration, and invasion in colorectal cancer by negatively regulating integrin α3β1 (ITGA3), which has been linked to intercellular communication and serves an important role in the signaling among cells and the extracellular matrix." (PMID 34884646, 2021). "In that study, it was also shown that ITGA3 levels are positively correlated with poor prognosis of patients with colorectal cancer and that knockdown of ITGA3 augments anoikis induction and reduces metastasis." (PMID 33435156, 2021). "ITGA3 is involved in cell proliferation, migration, and invasion in many cancers, including gastric, non-small cell lung, PCa and colorectal cancer, by activating the PI3K-Akt signalling pathway." (PMID 34366863, 2021). "High levels of ITGA3 correlate with more aggressive phenotypes and poor prognosis in patients with colorectal cancer and pancreatic ductal adenocarcinoma." (PMID 31953437, 2020). "In addition, it was suggested that miR-199a-5p overexpression suppresses the EMT of colorectal cancer cells, whereas the overexpression of ITGA3 restores this effect." (PMID 34884646, 2021). "Finally, the six selected genes (SIRT3, PIK3CA, ITGA3, DAPK1, PAK1, and CASP3) have been reported in colorectal cancer." (PMID 38213716, 2024). "In colorectal cancer (CRC) cells, miR-199a-5p has been shown to suppress cellular proliferation, as well as the migration and invasion capabilities of these cells, by inhibiting expression of ITGA3, a member of the integrin family." (PMID 37835506, 2023).
melanoma (10 papers, 2014 to 2024). A malignant, usually aggressive tumor composed of atypical, neoplastic melanocytes. "In aggregate, these findings suggest that ITGA3 is associated with super-enhancer–mediated regulation during melanoma cell dedifferentiation (phenotype switching) and in Epgn1/Epgn3 states." (PMID 38319712, 2024). "Utilizing CRISPR-Cas9 genome editing, we generated models of ITGA3 loss in the murine melanoma YUMMER1.7 (BrafV600E/WT, Pten–/–, Cdkn2–/–) cell line and in the human metastatic melanoma SKmel147 cell line." (PMID 38319712, 2024). "Other studies showed an opposite relationship: a correlation of ITGA3 protein expression with tumor thickness, higher ITGA3 expression on metastatic melanoma cell lines, and higher migration rates as compared with primary melanoma cell lines." (PMID 38319712, 2024). "One study reported reduced ITGA3 transcripts in melanoma cell lines and tumors of regional and distant metastasis compared with primary disease." (PMID 38319712, 2024). "Based on this effect of ITGA3 on cellular invasion and its super-enhancer profile in the Epgn3 invasive cell lines, we further investigated its role in melanoma biology." (PMID 38319712, 2024). "Investigating the expression of these genes in metastatic primary melanomas and metastases, we found that ITGA3 was downregulated in both regional and distant organ metastases compared to the metastatic primary lesions." (PMID 36091936, 2022). "Luciferase and expression assays in human melanoma samples confirmed that miR-214 targets the adhesion molecule integrin α3 (ITGA3) and transcription factor AP-2 gamma (TFAP2C)." (PMID 34943783, 2021). "Unexpectedly, ITGA3 promotes tumour growth in breast cancer, yet the oncogenic miR-214 downregulates it in melanoma." (PMID 34943783, 2021). "There are opposing data on ITGA3 expression during tumor progression in melanoma." (PMID 38319712, 2024). "We next examined bulk RNA-Seq data from TCGA melanoma tumor samples (n = 473), and the relationship between the proliferative, invasive, Epgn1, and Epgn3 signatures with MITF and ITGA3." (PMID 38319712, 2024). "Similar findings were noted in Cancer Cell Line Encyclopedia (CCLE) melanoma cell lines (n = 25) and an anticorrelation between MITF and ITGA3 was present (P = 0.002, OR, –0.54)." (PMID 38319712, 2024). "YUMMER1.7 melanoma cells stably expressing a nontargeted control (NTC) or ITGA3 KO were injected s.c. into the flanks of syngeneic C57BL/6J mice, and tumor volume was measured." (PMID 38319712, 2024). "Our in vitro and in vivo studies show that ITGA3 is a negative regulator of invasiveness, tumor progression, and metastatic potential in this context — roles that have not yet been described in melanoma." (PMID 38319712, 2024). "The role of ITGA3 in the context of phenotype switching in melanoma has never been described, to our knowledge." (PMID 38319712, 2024).
thyroid cancer (9 papers, 2019 to 2025). "In thyroid cancer, it has been reported that ITGA3 can govern PTC cell proliferation, invasion and migration and has been associated with recurrence and short survival." (PMID 39218967, 2024). "indicate that overexpression of ITGA3 significantly enhances the proliferation capability of thyroid cancer cell lines." (PMID 38144565, 2023). "The molecular mechanism of ITGA3 involved in the progression of thyroid cancer needs to be clarified by further experiments." (PMID 35174063, 2021). "In conclusion, our bioinformatics analysis and experiments demonstrate that ITGA3 is highly expressed in papillary thyroid carcinoma and is related to the progression of thyroid cancer and poor prognosis." (PMID 35174063, 2021). "ITGA3 gene expression was significantly correlated with clinicopathologic characteristics in TCGA thyroid cancer dataset." (PMID 35174063, 2021). "Heat map of the co-expression profile of ITGA3 in thyroid cancer was plotted by the UCSC Xena web-based tools." (PMID 35174063, 2021). "The expression level, association with clinicopathologic characteristics, co-expressed genes, signaling pathways of ITGA3 in thyroid cancer were comprehensively analyzed using bioinformatics analysis through multiple public gene databases." (PMID 35174063, 2021). "We identified a set of genes that were positively co-expressed with ITGA3 in thyroid cancer using GEPIA database, in which the tumor samples originated from TCGA database." (PMID 35174063, 2021). "The co-expressed genes with ITGA3 were analyzed using GEPIA database to explore ITGA3-related altered pathways in thyroid carcinoma." (PMID 35174063, 2021). "Analysis based on The Cancer Genome Atlas (TCGA) database showed that the expression of ITGA3 varies greatly in pathological stages, pathological types, tumor invasion stages, and lymph node metastasis stages of thyroid carcinoma." (PMID 35174063, 2021). "Collectively, miR‐524‐5p targeting on FOXE1 and ITGA3 prevents thyroid cancer progression through different pathways including cell cycling and autophagy." (PMID 30941771, 2019). "The literature reports that high expression of ITGA3 can promote proliferation, progression and invasion in various tumors, such as cholangiocarcinoma, thyroid carcinoma, pancreatic adenocarcinoma and glioma." (PMID 31844032, 2019). "Although we have initially explored the role of miRNA-144-5p/ITGA3 in the TC cell phenotype, further elucidation of its downstream pathways in thyroid cancer is indispensable, which is crucial for the development of effective diagnosis and treatment of thyroid cancer." (PMID 34938358, 2021). "In our cell experiments, knockdown of ITGA3 suppressed the proliferation, invasion, and migration capacity of thyroid cancer cells, suggesting ITGA3 may play an active role in PTC invasion and metastasis." (PMID 35174063, 2021). "Immunohistochemistry experiments showed that the expression of ITGA3 in recurrent thyroid cancer tissues was stronger than that in no-recurrent thyroid cancer tissues (P < 0.05)." (PMID 35174063, 2021). "Our findings suggested that the expression of ITGA3 and ERBB3 were closely correlated and may contribute to a signaling pathway in thyroid cancer." (PMID 35174063, 2021). "The α2β1 complex is the one with higher upregulation in thyroid carcinomas (up to 9-fold for ITGA2 vs. 2.5-fold for ITGA3 and ITGAV), although it is not the most abundant integrin expressed." (PMID 34208249, 2021). "Moreover, we examined whether coordinate signalling by ITGA3 and MET regulates the activation of PI3K/AKT signalling and ERK signalling, as MET and ITGA3 were both enriched in the same KEGG pathways in the thyroid cancer cluster." (PMID 40138447, 2025).
lymph node metastasis (8 papers, 2013 to 2025). "The results suggested that high expression of ITGA3 had a moderate diagnostic significance for lymph node metastasis of central neck and low diagnostic significance for regional invasion and recurrence." (PMID 35174063, 2021). "The analysis indicated that the expression of ITGA3 had a moderate diagnostic significance for lymph node metastasis in neck central area and low diagnostic significance for regional invasion and recurrence." (PMID 35174063, 2021). "The integrin subunit ITGA3 was associated with advanced disease stage, lymph node metastasis, extrathyroidal extension, high-risk, and a worst prognosis." (PMID 34208249, 2021). "Lymph node metastasis (LNM) was significantly associated with a high ITGA3/CD9 ratio (high-ITGA3/CD9), tumor size and T3-4, which relate to the extent of tumor invasion, and histopathological mode of invasion (YK4)." (PMID 24006899, 2013). "High ITGA3 expression was significantly associated with increased lymph node metastasis." (PMID 29988949, 2018). "The ROC analysis was conducted to evaluate the expression of ITGA3 for predicting lymph node metastasis, local invasion, and tumor recurrence." (PMID 35174063, 2021). "ITGA3 is overexpressed in PTC, especially in those with higher tumor invasion grades and lymph node metastasis, and was associated with recurrence and poor RFS of PTC." (PMID 35174063, 2021). "High expression level of ITGA3 was correlated with tumor regional invasion and lymph node metastasis." (PMID 35174063, 2021). "Multivariate analysis using logistic regression model showed that high expression of ITGA3 was a risk factor that associated with PTC recurrence and lymph node metastasis." (PMID 35174063, 2021). "A high rate (around 80%) of lymph node metastasis was found in cases with a high ITGA3/CD9 ratio (high-ITGA3/CD9) and invasive histopathology (YK4)." (PMID 24006899, 2013). "We adopted the same methods to explore the predictive value of ITGA3 for PTC lymph node metastasis." (PMID 35174063, 2021). "We report here that certain ITGA3/CD9 and ITGB4/JUP gene expression ratios are specifically related to individual clinical events such as lymph node metastasis, primary site recurrence, distant metastasis, and uncontrollable death from OSCC." (PMID 24006899, 2013). "For TCGA, the results showed ITGA3 was higher in lymph node metastasis-positive patients compared to lymph node-negative patients (p = 2.4 × 10−11)." (PMID 40138447, 2025). "The results showed that the expression level of ITGA3 in the group with lymph node metastasis was significantly higher than that without lymph node metastasis group in PTC (P < 0.01)." (PMID 35174063, 2021). "High expression of ITGA3 may have the potential role of predicting PTC recurrence and lymph node metastasis." (PMID 35174063, 2021). "ITGA3 expression in cases with lymph node metastasis was significantly higher than that in cases without lymph node metastasis (P < 0.01)." (PMID 35174063, 2021). "In the cohort of PTC from TCGA dataset, the expression level of ITGA3 in patients with lymph node metastasis was significantly higher than that without lymph node metastasis, presenting a positive correlation of ITGA3 gene expression with PTC lymph node metastasis." (PMID 35174063, 2021).